ENSG00000202059
Synonyms: LOC124900525
Gene: Small nucleolar RNA gene on chromosome 2 (203,052,285 to 203,052,418, reverse strand). Ensembl gene ENSG00000202059.
Gene Ontology:
Biological process: RNA processing
Cellular component: nucleolus
Homologues: Orthologues: rat LOC120099459 (77% identical). Paralogues in human: SNORA1B (90% identical), SNORA1 (89% identical).